LRRC7 (leucine rich repeat containing 7)
Description:
Adapter protein that is required for correct postsynapse architecture and regulates postsynaptic plasticity through interactions with different partners. Through its interaction with CACNA1C, it enhances trafficking of voltage-dependent L-type calcium channels to the dendritic cell membrane and increases channel postsynaptic clustering, thereby facilitating excitatory calcium signaling (By similarity). It also serves as a scaffold that brings CAMK2A and PPP1CA into close proximity, probably facilitating rapid dephosphorylation of CAMK2A by PPP1CA and influencing CAMK2A-mediated regulation of postsynaptic plasticity. Necessary for DISC1 and GRM5 localization to postsynaptic density complexes and for both N-methyl D-aspartate receptor-dependent and metabotropic glutamate receptor-dependent long term synaptic depression (By similarity).
Synonyms: Densin; KIAA1365; densin-180; MRD77
Gene: Protein-coding gene on chromosome 1 (69,567,922 to 70,151,945, forward strand). Ensembl gene ENSG00000033122.
Subcellular location: Cytoplasm; Postsynaptic density; Cell projection, dendritic spine; Postsynapse
Subcellular location (Human Protein Atlas): Cytosol; Plasma membrane; Centrosome; Nucleoplasm
Pathways (Reactome):
Neuronal System: Assembly and cell surface presentation of NMDA receptors; Long-term potentiation; Negative regulation of NMDA receptor-mediated neuronal transmission; Ras activation upon Ca2+ influx through NMDA receptor; Unblocking of NMDA receptors, glutamate binding and activation
Immune System: Neutrophil degranulation
Signal Transduction: RAF/MAP kinase cascade
Genetic constraint (gnomAD): Loss-of-function variants: 16 observed, 119.78 expected, observed/expected ratio (o/e) 0.13, 90% interval 0.089 to 0.2. The upper end of that interval is the gene's LOEUF score, 0.2, which puts it in group 1 of 6, group 1 being the genes least tolerant of losing a copy. Missense variants: 1,186 observed, 1,565.5 expected, observed/expected ratio (o/e) 0.76, 90% interval 0.72 to 0.8. Synonymous variants: 551 observed, 571.78 expected, observed/expected ratio (o/e) 0.96, 90% interval 0.9 to 1.03.
Homologues: Orthologues: pig LRRC7 (98% identical), chimpanzee LRRC7 (98% identical), dog LRRC7 (98% identical), macaque LRRC7 (97% identical), mouse Lrrc7 (94% identical), rat Lrrc7 (93% identical), guinea pig LRRC7 (90% identical), tropical clawed frog lrrc7 (72% identical), zebrafish lrrc7 (66% identical). Paralogues in human: ERBIN (38% identical), SCRIB (23% identical), LRRC1 (14% identical), PHLPP1 (13% identical), PHLPP2 (13% identical), MFHAS1 (12% identical), LRRK1 (10% identical), LRRD1 (10% identical), LRRC40 (9% identical), SHOC2 (9% identical), PIDD1 (9% identical), LRRIQ4 (9% identical), and 19 more.
Diseases named in the same sentence as LRRC7 in open-access papers:
LRRC7 is named in the same sentence as 19 diseases in open-access papers, as found by Europe PMC text mining. Sharing a sentence is not in itself a finding about the gene and the disease. The quoted sentences say what the papers report.
Intellectual disability (5 papers, 2022 to 2025). "Individuals with loss-of-function variants in LRRC7 consistently exhibit a phenotype characterized by intellectual disability, attention deficits, and global neurodevelopmental delay, including delays in motor and speech development." (PMID 40756776, 2025). "We have previously observed an association between high impact variants in LRRC7 and Intellectual Disability; also three individual cases with variants in LRRC7 had been described." (PMID 39256359, 2024). "Four genes each were associated with human educational attainment and intellectual disability, of which CHD2, NRG3 and LRRC7 were associated with both." (PMID 36056154, 2022).
emotional dysregulation (4 papers, 2019 to 2024). "Lrrc7 is a risk gene for both ASDs and emotional dysregulation in children, and iPSCs from schizophrenia patients display de novo mutations in Lrrc7." (PMID 38263132, 2024). "LRRC7 was also associated with emotional dysregulation and autistic traits, since LRRC7 KO mice had inappropriate juvenile aggressive behavior and significant anxiety-like behavior and social dysfunction in adulthood." (PMID 33246498, 2020). "In conclusion, Lrrc7 mutant mice provide a valuable tool to model childhood emotional dysregulation and persistent mental health comorbidities." (PMID 31582721, 2019). "Importantly, LRRC7 has recently been identified as a candidate gene for serious childhood emotional dysregulation." (PMID 31582721, 2019). "In conclusion, Lrrc7 mutant mice may provide a valuable tool to model developmental emotional dysregulation and persistent mental health difficulties." (PMID 31582721, 2019). "LRRC7 has been identified as a candidate gene for severe childhood emotional dysregulation." (PMID 31582721, 2019).
schizophrenia (4 papers, 2016 to 2024). A major psychotic disorder characterized by abnormalities in the perception or expression of reality. "It is further interesting that at least three of these genes (ADAMTS1, LRRC4C, and LRRC7) have already been associated with schizophrenia." (PMID 37244930, 2023). "At least seven genes putatively mapped by our significant non-reference TEs have been already associated with schizophrenia: LRRC4C, LRRC7, ST8SIA4, MGAM, ADAMTS1, MIR548AJ2 and SCN5A, which is also linked to the Brugada syndrome." (PMID 37244930, 2023).
attention deficit-hyperactivity disorder (3 papers, 2019 to 2024). A disorder characterized by a marked pattern of inattention and/or hyperactivity-impulsivity that is inconsistent with developmental level and clearly interferes with functioning in at least two settings (e.g. at home and at school). "A number of studies connect LRRC7 function to neurodevelopmental pathology, including ASD, language impairment, and attention deficit hyperactivity disorder." (PMID 33246498, 2020).
Anxiety (2 papers, 2019 to 2020). Intense feelings of nervousness, tension, or panic often arise in response to interpersonal stresses. "In mice, an Lrrc7 loss-of-function mutant line on the C57BL/6 genetic background has been reported to be small at weaning and to develop anxiety, excessive fighting, impaired short-term memory, and disrupted sensorimotor gating." (PMID 31582721, 2019). "Taken together, reduced expression of Lrrc7 had a profound impact on anxiety and social behavior on different genetic backgrounds, with manifestation influenced by rearing conditions." (PMID 31582721, 2019). "Consistent with a critical role of LRRC7 in emotional regulation, mutant mice had inappropriate juvenile aggressive behavior and significant anxiety-like behavior and social dysfunction in adulthood." (PMID 31582721, 2019). "Moreover, our data highlight an important role of LRRC7 in mGluR5 signaling, which is a potential new treatment target for anxiety and social dysfunction." (PMID 31582721, 2019).
B cell lymphoma (1 paper, 2025). "Even though, in a patient with B cell lymphoma (i.e., a cancer type resulting in impaired antibody production of B cells), a single nucleotide variation in LRRC7 was identified, which might indicate a role of this gene in regulation of antibody production in B cells." (PMID 41065049, 2025).
lung carcinoma (1 paper, 2022). "Examples of these such as FAT2 and LRRC7 have known roles in various cancers including lung cancer." (PMID 35999530, 2022).
prostate tumors (1 paper, 2025). "For instance, LE-2 cells showing high LRRC7 expression were absent in primary prostate tumors." (PMID 41468516, 2025).
cancer (5 papers, 2011 to 2025). A tumor composed of atypical neoplastic, often pleomorphic cells that invade other tissues. "Genes potentially associated with cell migration and cancer metastasis included CNTN5, FN1, Integrin Subunit Beta 6 (ITGB6), EPHB1, Unc-5 Netrin Receptor D (UNC5D), SDK1, RADIL, LRRC7, PCDH11X, and ADAMTS9." (PMID 39770638, 2024). "LRRC7 has been shown to interact with N-Cadherin and may thus provide a mechanism for transendothelial migration in cancer cells." (PMID 21731601, 2011).
neurodevelopmental disorder (3 papers, 2019 to 2025). A behavioral and cognitive disorder with onset during the developmental period that involves impaired or aberrant development of intellectual, motor, or social functions. "We show here that rare variants in LRRC7, coding for Densin-180, lead to a neurodevelopmental disorder in humans." (PMID 39256359, 2024). "Though defects in several genes coding for interaction partners of Densin-180 (CTNNB1; coding for β-catenin; CTNND2; coding for δ-catenin; SHANK2, SHANK3) are associated with neurodevelopmental disorders (NDD) in humans, LRRC7 has not yet been firmly established as an aetiological gene in humans." (PMID 39256359, 2024).
tumor (3 papers, 2019 to 2021). "Exosomal miR-25-5p enhances the movement of tumor cells trespassing the endothelial cells by inhibiting the expression of cell adhesion and migration-related protein leucine-rich repeat-containing protein 7 (LRRC7)." (PMID 31815633, 2019).
neurological disorder (1 paper, 2024). "In total, we identify 33 individuals with variants in LRRC7 affected by a neurological disorder." (PMID 39256359, 2024).
psychiatric disorder (1 paper, 2024). A disorder characterized by behavioral and/or psychological abnormalities, often accompanied by physical symptoms. "We identified 7 genes (Cap2, Shc3, Lrrc7, Rims2, Cntnap2, Tcf20, and Trank1) associated with neurodevelopmental and psychiatric disorders that feature social impairments." (PMID 38263132, 2024).
LRRC7 also shares sentences with these, for which no sentence is quoted: autism (1 paper); behavioural disorders (1); bipolar disorder (1); Brugada syndrome (1); gastric cancer (1); Obesity (1).